ATL2 (atlastin GTPase 2)
Description:
Atlastin-2 (ATL2) is a membrane-anchored GTPase that mediates the GTP-dependent fusion of endoplasmic reticulum (ER) membranes, maintaining the continuous ER network. It facilitates the formation of three-way junctions where ER tubules intersect. Two atlastin-2 on neighboring ER tubules bind GTP and form loose homodimers through the GB1/RHD3-type G domains and 3HB regions. Upon GTP hydrolysis, the 3HB regions tighten, pulling the membranes together to drive their fusion. After fusion, the homodimer disassembles upon release of inorganic phosphate (Pi). Subsequently, GDP dissociates, resetting the monomers to a conformation ready for a new fusion cycle (By similarity).
Synonyms: ATL-2; ARL6IP2; atlastin2; ARL3IP2; aip-2
Tractability: Antibody: UniProt predicts a signal peptide or a membrane-spanning region. PROTAC: ubiquitination databases record sites on it; its protein half-life has been measured.
Gene: Protein-coding gene on chromosome 2 (38,293,949 to 38,377,438, reverse strand). Ensembl gene ENSG00000119787.
Subcellular location: Endoplasmic reticulum membrane
Subcellular location (Human Protein Atlas): Endoplasmic reticulum
Pathways (Reactome):
Disease: Dengue Virus Genome Translation and Replication
Gene Ontology:
Molecular function: GTPase activity; GTPase-dependent fusogenic activity; protein binding; GTP binding
Biological process: endoplasmic reticulum membrane fusion; endoplasmic reticulum to Golgi vesicle-mediated transport; endoplasmic reticulum tubular network membrane organization; endoplasmic reticulum organization; protein homooligomerization
Cellular component: endoplasmic reticulum; endoplasmic reticulum membrane; endoplasmic reticulum tubular network membrane; membrane
Genetic constraint (gnomAD): Loss-of-function variants: 28 observed, 59.34 expected, observed/expected ratio (o/e) 0.47, 90% interval 0.35 to 0.65. The upper end of that interval is the gene's LOEUF score, 0.65, which puts it in group 2 of 6, group 1 being the genes least tolerant of losing a copy. Missense variants: 673 observed, 644.93 expected, observed/expected ratio (o/e) 1.04, 90% interval 0.98 to 1.11. Synonymous variants: 266 observed, 221.51 expected, observed/expected ratio (o/e) 1.2, 90% interval 1.09 to 1.33.
Homologues: Orthologues: rabbit ATL2 (99% identical), mouse Atl2 (98% identical), rat Atl2 (97% identical), chimpanzee ATL2 (94% identical), macaque ATL2 (94% identical), dog ATL2 (92% identical), guinea pig Atl2 (92% identical), pig ATL2 (92% identical), tropical clawed frog atl2 (78% identical), zebrafish atl2 (71% identical), Drosophila melanogaster atl (50% identical). Paralogues in human: ATL1 (62% identical), ATL3 (58% identical), GBP7 (22% identical), GBP4 (21% identical), GBP1 (21% identical), GBP2 (21% identical), GBP3 (20% identical), GBP6 (20% identical), RNF112 (20% identical), GBP5 (20% identical).
Diseases named in the same sentence as ATL2 in open-access papers:
ATL2 is named in the same sentence as 14 diseases in open-access papers, as found by Europe PMC text mining. Sharing a sentence is not in itself a finding about the gene and the disease. The quoted sentences say what the papers report.
breast carcinoma (2 papers, 2019 to 2023). "Interestingly, it predicted positive association in breast cancer through co-relation with MYL6, RABAC1 and other genes, while negatively regulating ATL2, ICE2 and TADA1 in melanoma and HCC." (PMID 30857225, 2019). "Thus, we analyzed whether ATL2 has a role in human breast cancer (BC) pathology." (PMID 37628611, 2023).
gastric cancer (2 papers, 2023 to 2025). A primary or metastatic malignant neoplasm involving the stomach. "ATL2 exons 3 and 4 are host sequences to a circular RNA, Hsa-circ 0000993, whose overexpression in gastric cancer cells resulted in decreased migration, invasion, and proliferation but without affecting ATL2 expression." (PMID 37628611, 2023). "ATL-2 from AMK • Inhibited proliferation and induced apoptosis• Reduced cell motility• Downregulated p-Akt and p-ERK• Increased Bax/Bcl-2 ratio• ATL-2 exerted significant anti-tumor effects on the gastric carcinoma cells by modulating Akt/ERK signaling pathway." (PMID 40144663, 2025).
breast tumors (1 paper, 2023). "The expression of ATL2 variant ATL2-2 was analyzed in breast tumors from the BC cohorts of the TCGA, METABRIC, and two independent Icelandic cohorts, Cohort 1 and 2; its association with clinical, pathological, survival, and cellular pathways was explored." (PMID 37628611, 2023). "Seventeen ATL2 transcripts were identified in TCGA breast tumors in the Xenabrowser database, and it is likely that some of them are incomplete transcripts due to the lack of 5′ and 3′ UTRs." (PMID 37628611, 2023). "We followed up on the ATL2-2 transcript because it was the only ATL2 transcript with higher expression in breast tumors than in normal tissue." (PMID 37628611, 2023). "The ATL2 transcripts found in breast tumors from TCGA were analyzed in the Xenabrowser database." (PMID 37628611, 2023). "However, comparing the four ATL2 transcripts between tumor and normal, only the ATL2 transcript ENST00000419554.6 was more highly expressed in breast tumors than in normal breast." (PMID 37628611, 2023). "Furthermore, ATL2 protein expression was assessed in 13 patient breast tumor samples and matched normal breast tissue with a C-terminus-specific antibody that detects the expression of the ATL2-2 isoform and potentially ATL2-3." (PMID 37628611, 2023).
dementia (1 paper, 2021). Loss of intellectual abilities interfering with an individual's social and occupational functions. "Additionally, in order to confirm the gene expression level of ATL2 in the brains of AD patients, we utilized publicly available data from the Allen Institute for Brain Science (Aging, Dementia, and TBI Study)." (PMID 34522215, 2021).
diabetes (1 paper, 2022). "In fact, each of the module components has been implicated with insulin, risk of diabetes or both in some manner (ADAM17, ATL2, MGP, SPLC2, N-methylproline, 3-methylhistidine)." (PMID 36329547, 2022).
Flavivirus Infections (1 paper, 2025). Infections with viruses of the genus FLAVIVIRUS, family FLAVIVIRIDAE. "We also demonstrate that ATL2 accumulates in areas of vRO formation during flavivirus infection." (PMID 41394679, 2025).
leukemia (1 paper, 2025). A malignant (clonal) hematologic disorder, involving hematopoietic stem cells and characterized by the presence of primitive or atypical myeloid or lymphoid cells in the bone marrow and the blood. "ATL2 dysfunction may impact ER stress responses, which may link to leukemogenesis and drug resistance in leukemia cells." (PMID 40375984, 2025).
Spastic paraplegia (1 paper, 2023). Complete loss of the ability to move the lower limbs accompanied by spasticity of the lower limbs. "In comparison to ATL1 in which mutations result in spastic paraplegia, which emphasizes the importance of a branched ER network in neuronal axons (and references therein), ATL2 may be important in filipods and other mechanisms involved in cellular migration." (PMID 37628611, 2023).
ZIKV infection (1 paper, 2024). "The fact that ZIKV infection promotes IGF2BP2 association with ATL2 led us to hypothesize that IGF2BP2 regulates vRNA replication by contributing to ZIKV replication organelle biogenesis." (PMID 39565347, 2024). "We have also demonstrated that ZIKV infection specifically induces the association between IGF2BP2 and ATL2, an ER-shaping protein which was previously reported to be required for DENV and ZIKV replication." (PMID 39565347, 2024).
infection (3 papers, 2021 to 2024). The state of being infected such as from the introduction of a foreign agent such as serum, vaccine, antigenic substance or organism. "Our study shows that the RING-H2-type E3 ubiquitin ligase, Arabidopsis Tóxicos en Levadura 2 (ATL2), is involved in response to fungal pathogen infection." (PMID 38397062, 2024). "Several of the ATL genes, including ATL2, ATL6, and ATL31, are rapidly induced in response to elicitors and pathogen infection." (PMID 34618142, 2021). "Intriguingly, ATL2/RBMX interaction was detected only in DENV-infected cells, suggesting that it is induced by the infection and might play a similar role as the one of IGF2BP2/ATL2 in case of DENV." (PMID 39565347, 2024). "However, ATL2 was reported to regulate DENV replication even if it does not associate with IGF2BP2 in that infection context." (PMID 39565347, 2024).
tumor (3 papers, 2023 to 2025). "The clinicopathological analyses revealed that the strongest association was between ATL2-2 mRNA levels and tumor size, grade, and molecular subtype." (PMID 37628611, 2023). "However, even after taking tumor size, grade, and molecular subtype into account in the survival analysis, high ATL2 mRNA remained associated with BCSS in the estrogen-receptor-positive luminal group in the METABRIC cohort." (PMID 37628611, 2023). "Based on the reported ATL2 functions, there are numerous ways that ATL2 could support cell proliferation and potential tumor progression." (PMID 37628611, 2023). "ATL2 could also support tumor progression by affecting proteins in the ER (FAM134B)." (PMID 37628611, 2023).
cancer (1 paper, 2023). A tumor composed of atypical neoplastic, often pleomorphic cells that invade other tissues. "The dysregulation of ATL2, located at ER network junctions, has been associated with cancer." (PMID 37628611, 2023). "Enhanced expression of the ATL2-2 variant may offset the balance in the ER, making the cytoplasmic environment more fit to support cancer mechanisms." (PMID 37628611, 2023).
ATL2 also shares sentences with these, for which no sentence is quoted: melanoma (1 paper); Zinc deficiency (1).